INS (insulin)
Diseases named in the same sentence as INS in open-access papers (continued):
Sharing a sentence is not in itself a finding about the gene and the disease.
Insulin resistance (continued). "Impairment of insulin signaling transduction is a feature in insulin resistance (IR), and it can compromise PM GLUT4 translocation." (PMID 33430527, 2021). "A recent study reported that men with the GG genotype of the FSH receptor rs6166 SNP have lower levels of blood glucose than those with the AA genotype and their FSH concentrations were inversely correlated with insulin and insulin resistance." (PMID 35059409, 2021). "Serum fasting insulin and glucose concentration were analyzed, the homeostatic model assessment-insulin resistance (HOMA-IR) index was calculated." (PMID 33451031, 2021). "The impaired ability of insulin to suppress endogenous glucose and free fatty acids (FFAs) production is indicative hepatic insulin resistance." (PMID 34307250, 2021). "Even small doses of RES can have an effect, as in the case of 10 mg RES, which significantly decreased insulin resistance via the Akt pathway, which led to improved insulin sensitivity in type II diabetes patients." (PMID 34578972, 2021). "In particular, TNF-α aggravates insulin resistance via activation of c-Jun kinase, which inhibits the phosphorylation of insulin receptor substrate-1 and hence blocks insulin signaling, resulting in exacerbation of the inflammatory response." (PMID 34366841, 2021). "Along with peripheral insulin resistance and defects in insulin secretion, other unbalanced metabolic processes, including glucotoxicity and lipotoxicity, oxidative stress and low-grade inflammation are already evolving in the state of prediabetes." (PMID 34439410, 2021). "The tissue-specific Myo-inositol (MI) and D-chiro-inositol (DCI) ratio is modulated by insulin through aromatase and is altered in insulin resistance (IR), with reduced epimerization of MI to DCI in insulin-sensitive tissues." (PMID 33706732, 2021). "When measuring insulin resistance, researchers have found that fasting insulin levels and HOMA-IR correlate well with the gold standard hyperinsulinemic euglycemic clamp method." (PMID 34072554, 2021). "Children born SGA, like those born LGA, have been shown to have an increased insulin resistance in childhood, but studies have also shown increased insulin sensitivity at birth in SGA children." (PMID 33544169, 2021). "This means that the beta cells of the pancreas are simply producing less insulin because the lowered insulin resistance has decreased the demand for insulin production." (PMID 34578984, 2021). "Fasting insulin concentrations and insulin resistance increase during pregnancy, especially in the 2nd and 3rd trimester, as observed between T0 and T1 in this study." (PMID 33673568, 2021). "Offspring born to women with poor glycemic control also have higher blood glucose and insulin levels, decreased insulin sensitivity as measured by Homeostatic Model Assessment of Insulin Resistance (HOMA-IR), and higher blood pressure at 9.5 years of age4." (PMID 34155315, 2021). "The increase in adipose tissue and impaired insulin signal transduction increase insulin resistance by approximately 56%, while progesterone can lower the expression of IRS-1 to inhibit glucose uptake by adipocytes." (PMID 35059395, 2021). "This shows that the higher BMI, the more serious the accumulation of adipocytes, the more MIF and insulin secretion, the more serious the impact on occurrence of insulin resistance and tumor progression." (PMID 34485124, 2021). "Consistent with this, it has also been observed that mice fed HFD have higher glucose and insulin basal concentrations, insulin resistance, and glucose intolerance." (PMID 34066406, 2021). "Measurement of fasting insulin as a surrogate for insulin resistance is also limited by the multitude of different assays used for the determination of insulin." (PMID 34572220, 2021). "In our setting, GSK0660 alone increases circulating levels of insulin an indicator of insulin resistance." (PMID 33924880, 2021).
Insulin resistance (continued). "Insulin resistance is a diminished ability of cells to respond to the physiological actions of insulin." (PMID 34220716, 2021). "Routine GDM biomarkers (plasma glucose, insulin, C-peptide, homeostatic model assessment of insulin resistance, and sex hormone-binding globulin) can differentiate between healthy pregnant women and those with GDM but are not suitable for early GDM diagnosis." (PMID 34658643, 2021). "Since its discovery, GLP-1 has emerged as an incretin hormone for its facilitation in insulin release and reduction of insulin resistance (IR)." (PMID 34552561, 2021). "IPGTT and insulin signaling results further confirmed abnormal glucose tolerance and insulin resistance in HIF1αKOMBH mice." (PMID 34733235, 2021). "One of the factors stimulating metabolic syndrome is insulin resistance, which is impaired sensitivity of tissues to insulin, the hormone regulating the glucose concentration in the blood." (PMID 34578858, 2021). "Nevertheless, to the best of our knowledge, this is the first systematic study investigating the impact of PM2.5 on insulin resistance-related hepatic inflammation and the insulin signaling pathway in a rat model." (PMID 34745386, 2021). "The bioactive components in these seeds like chlorogenic acid in sunflower seeds and secoisolariciresinol diglucosoid are involved in the treatment of insulin resistance or insulin production." (PMID 34540481, 2021). "T2DM is defined as low insulin production by pancreatic β-cells, coupled with peripheral insulin resistance." (PMID 33668426, 2021). "Two main forms of DM are described: type 1 (or T1DM), which is caused by genetic deficiency in insulin release, and type 2 (or T2DM), which is caused by insulin resistance and has mixed genetic and lifestyle determinants." (PMID 33946846, 2021). "High saturated fatty acid levels, which can suppress normal IRS1 tyrosine phosphorylation and induce insulin resistance in skeletal muscle, show a correlation with skeletal muscle insulin activity." (PMID 34489627, 2021). "Since insulin resistance is the early abnormality in the pathogenesis of type 2 diabetes, there has been ample interest for characterizing insulin-sensitizing agents for the disease management." (PMID 34073781, 2021). "Insulin resistance is a consequence of disturbed endocrine regulation of insulin, the key controller of body energy storage and mobilization." (PMID 34836068, 2021). "Indices of insulin sensitivity or insulin resistance determined by fasting insulin concentrations such as HOMA-IR will potentially overestimate whole-body insulin resistance in the context of excess liver TG and impaired insulin clearance." (PMID 33498493, 2021). "Exploratory outcomes include differences in 6-month changes in fasting insulin, homeostasis model assessment of insulin resistance, diastolic blood pressure, waist circumference, and 10-year cardiovascular disease risk." (PMID 33522954, 2021). "T2DM is a chronic endocrine disorder characterized by hyperglycaemia, insulin resistance, ineffective insulin secretion by the pancreas, and increased hepatic glucose production." (PMID 34451903, 2021). "Calculation of the homeostatic model assessment of insulin resistance (HOMA‐IR) identified Rptorob−/− mice as being more insulin‐sensitive than HFD‐fed control mice." (PMID 33977204, 2021). "Firstly, it is known that pregnancy is characterized by a state of insulin resistance, favored by a surge in local and placental hormones, which is overcome through compensatory insulin secretion by the pancreatic β-cells." (PMID 34206854, 2021). "WSD-fed dams also had increased insulin AUC during an i.v. glucose tolerance test compared with CD-fed females, as previously observed, supporting development of insulin resistance." (PMID 34935645, 2021). "Insulin resistance remains at the top of the NAFLD mechanism, and serum insulin levels are associated with lobular inflammation and hepatocyte ballooning." (PMID 34578867, 2021).
Insulin resistance (continued). "Hyperinsulinemia is known to lead to insulin resistance in mammals by downregulating the mediators of the insulin signaling pathway." (PMID 34358068, 2021). "T2DM is characterized by changes in beta-cell mass, decreased insulin secretion, and elevation in intestinal glucose absorption, upsurge in glucagon secretion, increase in insulin breakdown, insulin resistance, and increased levels of catecholamines." (PMID 35106234, 2021). "In the case of insulin resistance, normal circulating levels of insulin are inadequate to elicit normal insulin responses in adipose, muscle and liver tissues, resulting in hyperglycemia and hyperlipidemia, ultimately metabolic syndrome." (PMID 34122092, 2021). "Humans with systemic insulin resistance have been reported to show attenuated insulin-evoked brain responses." (PMID 34331964, 2021). "The HOMA, as primary endpoint, was used to detect the insulin resistance and function of pancreatic beta-cells (which produce insulin)." (PMID 34684666, 2021). "With the increased adiposity, D1KO mice had increased fed insulin levels and displayed glucose intolerance and insulin resistance as assessed by GTT and ITT, respectively." (PMID 34824202, 2021). "The emerging role of the tight connection between liver outcomes and improvements in insulin resistance across the clinical studies suggest that insulin sensitivity should be addressed as a solid endpoint of lifestyle interventions." (PMID 34201382, 2021). "Or similar to conditions of T2DM, patients given exogenous insulin, serves only to mask the downstream problem (hyperglycaemia), while increasing hyperinsulinaemia and insulin resistance, driving the disease further." (PMID 34572351, 2021). "Such dietary changes have elevated insulin resistance that requires higher insulin secretion to maintain normoglycemia." (PMID 33923450, 2021). "Women with PCOS displayed profound insulin resistance with higher levels of fasting insulin and a ~50% reduction in insulin sensitivity as measured by euglycaemic–hyperinsulinaemic clamp (P < 0.05)." (PMID 34707569, 2021). "A number of studies have reported increased insulin resistance and reduced insulin sensitivity in patients with hyperprolactinaemia, supported by in vitro studies in the field." (PMID 33902531, 2021). "It is reported that ROS have been playing a significant function in FFA-induced insulin resistance by insulin receptor substrate-1 phosphorylation in serine residue and by inhibiting downstream insulin signaling." (PMID 34201185, 2021). "Group III rats manifest features of severe insulin resistance which is evidenced by the elevations in the fasting serum insulin levels." (PMID 34946771, 2021). "In healthy and obese children, the relationships between GAL serum levels and metabolic parameters (insulin, glucose, lipids, homeostasis model assessment-insulin resistance, leptin) have been studied." (PMID 33802616, 2021). "While the underlying molecular mechanisms remain to be identified, reduced insulin clearance appears to be an early adaptive response to insulin resistance." (PMID 34206745, 2021). "Excessive ROS can inhibit insulin-induced energy uptake in fat and muscle tissues, damage islet beta cells, inhibit insulin secretion, and aggravate insulin resistance." (PMID 33628835, 2021). "Insulin resistance (IR) is characterized by a reduced action of insulin despite increased insulin concentrations (hyperinsulinemia)." (PMID 35242790, 2021). "The missense loss-of-function mutation AKT2-Arg274His leads to hyperinsulinemia and insulin resistance in humans, highlighting the importance of AKT2 in mediating insulin signalling." (PMID 33893069, 2021). "GLP-1RAs increase the sensitivity of β cells to glucose and positively reduce insulin resistance to further promote insulin secretion." (PMID 34131405, 2021). "Both high blood glucose and abnormal lipid metabolism can affect insulin activity and exacerbate the insulin resistance." (PMID 34702218, 2021).
Insulin resistance (continued). "In obese or overweight patients with type 2 diabetes who have insulin resistance due to overnutrition and a positive energy balance, endothelial function is potentially impaired by high-dose insulin therapy due to selective insulin resistance." (PMID 34439553, 2021). "Studies regarding PTP-1B roles carried out on knockout mice revealed that this enzyme augments insulin sensitivity and enhances receptor Tyr phosphorylation and is impervious to the development of obesity and insulin resistance induced by high-fat diets." (PMID 34068151, 2021). "Our results are consistent with the demonstrated existence of active cross-talks between angiotensin II and insulin signaling, as well as a role of sub inflammation in contributing to insulin resistance in obese hypertensive subjects." (PMID 34107965, 2021). "Muscle mitsugumin 53 (MG53), a newly identified muscle-specific protein, is one pivotal element of insulin resistance in type 2 diabetes by participating in the insulin degradation process through insulin receptor substrate-1 (IRS-1) and the p-AKT pathway." (PMID 34163437, 2021). "Imbalances in relation to insulin metabolism (insulin resistance) precede the development of multiple single and clustered cardiometabolic risk factors which precede the development of cardiometabolic diseases." (PMID 34444178, 2021). "Insulin resistance, which is defined as impaired ability of cells, such as hepatocytes, adipocytes, and skeletal muscle cells to respond to the action of insulin, plays an essential role in the development of type 2 diabetes, obesity, and metabolic syndrome." (PMID 33510836, 2021). "In T2DM patients, the pancreas produces and releases insulin, but the cells become resistant so that the insulin is ineffective, a state that is referred to as insulin resistance [IR]." (PMID 33918509, 2021). "High concentrations of hepatic glucose and plasmatic insulin are recognized as biomarkers of hepatic insulin resistance." (PMID 34083664, 2021). "Several evidences show that a single bout of exercise is capable to increase insulin-mediated glucose uptake in healthy subjects, as well as in subjects with insulin resistance." (PMID 32737757, 2021). "Treatment of diabetic rats with MLT significantly normalized the levels of serum glucose, HbA1-c, and the lipid profile and improved the insulin levels and insulin resistance compared with diabetic rats, affirming its antidiabetic effect." (PMID 33748504, 2021). "Insulin resistance is a pathophysiological disorder, which arises as a result of decreased insulin sensitivity in peripheral tissues." (PMID 34960064, 2021). "Following the digestion of the meal and as fasting progresses during the night, the ratio insulin/glucagon decreases, and metabolism gradually moves from an anabolic into a catabolic state by the development of insulin resistance, which peaks at dawn." (PMID 33419065, 2021). "It is known that both acute and chronic administration of glucocorticoids induce insulin resistance in skeletal muscle and are accompanied by high insulin levels." (PMID 35052508, 2021). "The hallmarks of insulin resistance include increased fasting insulin and changes in the lipid profile, such as increased triglycerides and decreased high density lipoprotein (HDL) cholesterol." (PMID 33613319, 2021). "The inhibition of insulin/IGF-1 signaling evokes insulin resistance, a condition known to be increased with aging." (PMID 34476533, 2021). "The obese db/db mouse is insulin-resistant and exhibits basal hyperinsulinemia, thus resembling human obese type 2 diabetes with peripheral insulin resistance." (PMID 33983968, 2021). "Mkp5 is necessary for the obesity‐induced insulin response and can prevent the development of insulin resistance and metabolic abnormalities." (PMID 34647385, 2021). "ADMSCs restore hyperglycemia, insulin resistance, insulin sensitivity, and glucose metabolism in T2DM by restoring inflammation and ER stress in the pancreas and liver." (PMID 34722505, 2021).
Insulin resistance (continued). "Mice with increased JAZF1 expression showed marked improvement in insulin resistance and metabolic profile with reduced fasting plasma insulin and glucose levels." (PMID 34440550, 2021). "For EDIH, the percent change in biomarker concentration in the insulin-related biomarkers ranged from +1.3% (glucose) to +8% (homeostatic model assessment for insulin resistance) and −9.7% for IGF-binding protein-1." (PMID 34616762, 2021). "Insulin resistance occurs when normal circulatory insulin concentration become insufficient for promoting glucose uptake and subsequent intracellular glucose homeostasis." (PMID 34576943, 2021). "Long-term exposure to HCD appears to result in diabetic changes, such as insulin resistance, with downregulated insulin/insulin-like growth factor signaling in flies." (PMID 35059137, 2021). "Insulin resistance is a state of decreased responsiveness of target tissues to insulin, and a major feature of type 2 diabetes, glucose intolerance, hypertension, dyslipidemia, and cardiovascular disease." (PMID 33402193, 2021). "The HSD-fed flies also developed insulin resistance, as shown by the reduced phosphorylation of Akt in response to insulin, as well as obesity, as indicated by increased lipid storage in the fat body adipocytes (F′)." (PMID 34830305, 2021). "It is essential to note that s307 contributes to insulin resistance, but its phosphorylation is also critical in the physiological insulin cascade." (PMID 33995826, 2021). "The presence of unresolved hyperglycemia and prolonged increased insulin secretion also contribute to worsening insulin resistance over time." (PMID 33868167, 2021). "Increased insulin resistance and decreased insulin secretion can adversely affect blood glucose level, blood pressure, and blood lipid levels, increasing the risk of developing DR." (PMID 33790305, 2021). "Both processes were identified as features of either insulin resistance (fission) or proper insulin signaling (fusion) in cell-based and animal models of insulin resistance as well as in obese and/or T2D subjects." (PMID 33815291, 2021). "Blood glucose and plasma insulin levels in the fasted state as well as the calculated insulin resistance (HOMA-IR) were similar in all mice." (PMID 33536239, 2021). "Since then, insulin has been found to regulate glucose and lipid metabolism in cells, and the alterations of these functions contribute to development of insulin resistance and T2DM." (PMID 34440929, 2021). "Allopregnanolone therapy improved working spatial memory and biochemical markers of metabolic syndrome (serum glucose, insulin, insulin resistance, lipid profile)." (PMID 34063474, 2021). "A hallmark of being overweight and obesity is the development of insulin resistance in the skeletal muscle, which is the main site of post-prandial insulin-dependent glucose uptake, and this process requires GLUT4 translocation." (PMID 34638553, 2021). "T2DM is characterized by an impaired β-pancreatic cell function and insulin secretion, hyperglycemia and insulin resistance, and recently the epigenetic regulation of β-pancreatic cells differentiation has been underlined as being involved." (PMID 34140928, 2021). "Insulin resistance is defined as the increased requirement for insulin to maintain glucose homeostasis and it is a consistent finding in patients affected by T2D." (PMID 34639123, 2021). "Our findings agree with some authors that described a rapid improvement in insulin resistance, mainly reducing insulin levels after RYGB." (PMID 33593418, 2021). "By comparison of hormonal profile of the participants in the four phenotypes, we found a significant difference in the insulin level and insulin resistance that was higher in patients with classic PCOS phenotype (both P < 0.001)." (PMID 33750349, 2021).